NSD2 (nuclear receptor binding SET domain protein 2)
Description:
Histone methyltransferase which specifically dimethylates nucleosomal histone H3 at 'Lys-36' (H3K36me2). Also monomethylates nucleosomal histone H3 at 'Lys-36' (H3K36me) in vitro. Does not trimethylate nucleosomal histone H3 at 'Lys-36' (H3K36me3). However, specifically trimethylates histone H3 at 'Lys-36' (H3K36me3) at euchromatic regions in embryonic stem (ES) cells (By similarity). By methylating histone H3 at 'Lys-36', involved in the regulation of gene transcription during various biological processes. In ES cells, associates with developmental transcription factors such as SALL1 and represses inappropriate gene transcription mediated by histone deacetylation (By similarity). During heart development, associates with transcription factor NKX2-5 to repress transcription of NKX2-5 target genes (By similarity). Plays an essential role in adipogenesis, by regulating expression of genes involved in pre-adipocyte differentiation. During T-cell receptor (TCR) and CD28-mediated T-cell activation, promotes the transcription of transcription factor BCL6 which is required for follicular helper T (Tfh) cell differentiation (By similarity). During B-cell development, required for the generation of the B1 lineage (By similarity). During B2 cell activation, may contribute to the control of isotype class switch recombination (CRS), splenic germinal center formation, and the humoral immune response (By similarity). Plays a role in class switch recombination of the immunoglobulin heavy chain (IgH) locus during B-cell activation (By similarity). By regulating the methylation of histone H3 at 'Lys-36' and histone H4 at 'Lys-20' at the IgH locus, involved in TP53BP1 recruitment to the IgH switch region and promotes the transcription of IgA (By similarity). [Isoform 1]: Histone methyltransferase which specifically dimethylates nucleosomal histone H3 at 'Lys-36' (H3K36me2). [Isoform 4]: Histone methyltransferase which specifically dimethylates nucleosomal histone H3 at 'Lys-36' (H3K36me2). Methylation of histone H3 at 'Lys-27' is controversial. Mono-, di- or tri-methylates histone H3 at 'Lys-27' (H3K27me, H3K27me2 and H3K27me3). Does not methylate histone H3 at 'Lys-27'. May act as a transcription regulator that binds DNA and suppresses IL5 transcription through HDAC recruitment.
Synonyms: MMSET; TRX5; WHSC1; KMT3G; KMT3F; RAUST; REIIBP; WHS
Tractability: Small molecule: a structure with a bound ligand is known; a high-quality ligand is known. PROTAC: ubiquitination databases record sites on it; a small molecule that binds it is known.
Target class: Writer; Protein methyltransferase; SET domain; Epigenetic regulator
Chemical probes: UNC6934 (high quality), UNC8732 (high quality)
Gene: Protein-coding gene on chromosome 4 (1,870,559 to 1,982,207, forward strand). Ensembl gene ENSG00000109685.
Subcellular location: Nucleus; Chromosome; Nucleus (Isoform 1); Nucleus (Isoform 3); Cytoplasm (Isoform 4); Nucleus, nucleolus
Subcellular location (Human Protein Atlas): Nucleoplasm; Nucleoli
Pathways (Reactome):
DNA Repair: Nonhomologous End-Joining (NHEJ); Processing of DNA double-strand break ends; Recruitment and ATM-mediated phosphorylation of repair and signaling proteins at DNA double strand breaks
Cell Cycle: G2/M DNA damage checkpoint
Chromatin organization: PKMTs methylate histone lysines
Gene Ontology:
Molecular function: histone H3K36 dimethyltransferase activity; histone H3K36 methyltransferase activity; protein binding; histone H3 methyltransferase activity; histone H4K20 methyltransferase activity; chromatin binding; histone H3K36 trimethyltransferase activity; histone methyltransferase activity; sequence-specific DNA binding
Biological process: double-strand break repair; regulation of DNA-templated transcription; chromatin remodeling
Cellular component: chromosome; cytoplasm; nucleolus; nucleoplasm; nucleus; nuclear lumen
Genetic constraint (gnomAD): Loss-of-function variants: 12 observed, 139.91 expected, observed/expected ratio (o/e) 0.0858, 90% interval 0.054 to 0.14. The upper end of that interval is the gene's LOEUF score, 0.14, which puts it in group 1 of 6, group 1 being the genes least tolerant of losing a copy. Missense variants: 1,148 observed, 1,807.7 expected, observed/expected ratio (o/e) 0.64, 90% interval 0.6 to 0.67. Synonymous variants: 667 observed, 673.69 expected, observed/expected ratio (o/e) 0.99, 90% interval 0.93 to 1.05.
Gene-disease validity (ClinGen):
ClinGen rates the evidence that NSD2 causes each of these diseases.
syndromic intellectual disability (autosomal dominant): Definitive. A intellectual disability that is part of a larger syndrome.
Homologues: Orthologues: chimpanzee NSD2 (99% identical), macaque NSD2 (98% identical), mouse Nsd2 (91% identical), dog NSD2 (91% identical), guinea pig NSD2 (90% identical), rat Nsd2 (86% identical), tropical clawed frog nsd2 (66% identical), pig NSD2 (64% identical), zebrafish nsd2 (46% identical), Drosophila melanogaster ash1 (15% identical), Caenorhabditis elegans met-1 (13% identical), Drosophila melanogaster Set2 (13% identical), and 15 more. Paralogues in human: NSD3 (45% identical), NSD1 (45% identical), SETD2 (21% identical), ASH1L (16% identical), KMT2A (14% identical), KMT2D (12% identical), EZH1 (12% identical), KMT2B (12% identical), KMT2C (12% identical), EZH2 (11% identical), EHMT1 (11% identical), EHMT2 (11% identical), and 7 more.
Diseases named in the same sentence as NSD2 in open-access papers:
NSD2 is named in the same sentence as 140 diseases in open-access papers, as found by Europe PMC text mining. Sharing a sentence is not in itself a finding about the gene and the disease. The quoted sentences say what the papers report.
multiple myeloma (116 papers, 2010 to 2026). "In multiple myeloma, expansion of H3K26me2 and shrinkage of H3K27me3 domains as a result of NSD2 overexpression were shown to be linked to chromatin changes in TADs and CTCF loops as well as disruptions in gene expression." (PMID 37016431, 2023). "Of interest, a similar action has been revealed for the human 4; 14 translocation causing myeloma upon NSD2 overexpression, which is also associated with H3K36me2-insulated domains shrinking H3K27me3 involving 3D organization." (PMID 37684044, 2023). "This translocation is found in approximately 20% of patients with multiple myeloma and is associated with NSD2 and FGFR3 (co-amplified) overexpression, though NSD2 is purported to exert the primary oncogenic role." (PMID 36360250, 2022). "NSD2 also has been linked to several cancers, such as prostate cancer and multiple myeloma, and it is also the target of translocations in multiple myeloma." (PMID 24874471, 2014). "NSD2 is associated with tumor aggressiveness or prognosis in most types of cancers, including prostate cancer and multiple myeloma and is overexpressed in at least 15 different cancers." (PMID 25494638, 2014). "In addition, WNT and MAPK (Ras-related) pathways were identified in two out of the three lines examined and have also previously been linked to NSD2 in the multiple myeloma model." (PMID 37016431, 2023). "On the contrary, NSD2 hyper-activation caused by either point mutations or genomic translocations represents a relevant cause of B-cell-associated hematological malignancies, such as multiple myeloma and acute leukemia, and other types of cancers including colon cancer and lung carcinoma." (PMID 36232375, 2022). "In multiple myeloma, metabolic reprogramming by NSD2-PKCα axis induces resistance to lenalidomide, an immunomodulatory agent." (PMID 41301842, 2025). "In recent years, NSD2 expression is found to be overexpressed in multiple myeloma, colon cancer, prostate cancer, and lung cancer." (PMID 40097917, 2025). "Studies using CRISPR/Cas9, RNA interference, and degrader approaches have confirmed that NSD2 and its reader domains are essential for myeloma cell survival, chromatin targeting, and maintaining oncogenic gene expression." (PMID 40563566, 2025). "In multiple myeloma, NSD2 has been identified as a component of transcriptional corepressor complexes comprising HDACs, mSin3a, and LSD1 demethylase." (PMID 41301842, 2025). "The histone methyltransferase NSD2 is associatedwith several typesof cancers such as ALL, multiple myeloma, and prostate cancer." (PMID 38687638, 2024). "The addition of UNC8153 to multiple myeloma lines resulted in dose- and time-dependent decreases in NSD2 and H3K36me2, as well as changes in cancer-related phenotypes." (PMID 38353483, 2024). "PARP1 interacts with NSD2 and catalyzes PARylation of NSD2 upon oxidative stress, leading to decreased histone methyltransferase activity of NSD2 and impaired NSD2 recruitment to target genes in multiple myeloma." (PMID 36909172, 2023). "NSD2 (nuclear receptor binding SET domain protein 2), also named MMSET (multiple myeloma SET domain), catalyzes H3K36me2 formation and has been associated with cancer." (PMID 37228649, 2023). "The lack of effective agents to inhibit the enzymatic activity of NSD2 has hampered targeted therapy for NSD2 rearranged multiple myeloma and NSD2 E1099K relapsed ALL." (PMID 37016431, 2023). "Using high-throughput compound screenings, 5-Aminonaphthalene derivatives have emerged very recently as selective inhibitors of NSD2 activity in multiple myeloma and acute lymphoid leukemia cell lines." (PMID 36232375, 2022). "We and others showed that super-enhancers were associated to key genes contributing to myeloma pathogenesis, such as MYC, IRF4, CCND1, NSD2 and MAF39,66." (PMID 35198065, 2022).
multiple myeloma (continued). "Given that NSD2 is known to play a relevant role in multiple myeloma relapse and treatment resistance, genetic and epigenetic compounds should be found capable of inhibiting NSD2 activity regardless of the nature of its alteration." (PMID 36232375, 2022). "The altered expression of NSD2 can affect global histone methylation enrichment and high order chromatin organization, leading to the development of diseases such as multiple myeloma or lung cancer." (PMID 36232375, 2022). "The first validated peptide specific inhibitor against the catalytic activity of NSD2 in multiple myeloma cases was PTD2, whose inhibitor effect is specific in the presence of the cofactor S-adenosyl-L-methionine (SAM)." (PMID 36232375, 2022). "In summary, our present findings elucidated the importance of SRC-3 in proteasome-inhibitor-induced drug resistance in myeloma cells, and uncovered its interaction with the histone methyltransferase NSD2." (PMID 33589584, 2021). "Studies have revealed that NSD2 is important for the proliferation and/or survival of different types of human cancer cells, including myeloma cells, leukemia cells, prostate cancer cells, and osteoblastoma cells." (PMID 34671018, 2021). "An upregulation of NSD2, a histone H3 lysine 36 (H3K36) methyltransferase is linked to multiple myeloma and other types of cancer." (PMID 34782608, 2021). "Studies have shown that increased H3K36me2 in NSD2-overexpressed multiple myeloma cells is important for the transcription activation of several key oncogenes, including SYK and MYK." (PMID 34671018, 2021). "Akin to the in vitro results, when NSD2 was depleted in myeloma cells, the reassembly of GFP-SRC-3 FL was significantly inhibited, whereas it was enhanced when NSD2 was overexpressed in vivo." (PMID 33589584, 2021). "Our results indicate the regulation of NSD2 stability by BRCA1-mediated ubiquitination as a potential therapeutic target process in multiple myeloma." (PMID 32826945, 2020). "Nuclear SET domain-containing 2 (NSD2), also known as WHSC1 (Wolf-Hirschhorn syndrome candidate 1) or MMSET (multiple myeloma SET domain), belongs to the NSD family of histone methyltransferases." (PMID 33665162, 2020). "In multiple myeloma, a 4;14 translocation induces overexpression of the histone methyltransferase, NSD2, resulting in expansion of H3K36me2 and shrinkage of antagonistic H3K27me3 domains." (PMID 31649247, 2019). "Overexpressed NSD2 in myeloma cells is known to significantly increase the level of H3K36 dimethylation, followed by a striking decrease in H3K27 methylation." (PMID 31727171, 2019). "Set2 enzyme NSD2 is overexpressed in multiple myeloma, bladder, and several other cancers, which correlates with poor prognosis, making these enzymes potential drug targets." (PMID 31439846, 2019). "Although the use of EZH2 inhibitors in the context of NSD mutations has not been studied, one recent report suggested a promising mechanism for application of EZH2 inhibitors in NSD2-overexpressing myeloma cells." (PMID 29176703, 2017). "Previous work demonstrated that the methyltransferase activity of NSD2 is required to mediate the effects on proliferation in myeloma cells." (PMID 27604143, 2016). "WHSC1, also known as NSD2 (nuclear receptor SET domain containing) and MMSET (multiple myeloma SET domain containing), encodes a putative histone methyltransferase with features of a transcriptional co-repressor." (PMID 24626991, 2014). "Increased NSD2 activity is also reported during tumor proliferation in glioblastoma and myeloma, resulting in aberrantly high global levels of H3K36me2." (PMID 25494638, 2014). "The oncogenic role of NSD2 was first discovered in multiple myeloma." (PMID 40097917, 2025). "NSD2 overexpression is a characteristic feature of the translocation in multiple myeloma." (PMID 39163297, 2024). "Targeting NSD2, especially in multiple myeloma, holds potential for cancer therapy." (PMID 39163297, 2024).
multiple myeloma (continued). "However, NSD2 enzymatic activity is not only altered upon chromosome translocation in myeloma patients." (PMID 36232375, 2022). "The overexpression of NSD2 in multiple myeloma is a consequence of its regulation by a strong IgH enhancer in the NSD2 gene, and this NSD2 overexpression impairs the binding of EZH2 and the reprogramming of the myeloma epigenome because of locally altering the H3K36 and H3K27 methylation patterns." (PMID 36011043, 2022). "Intriguingly, we found that the half-life of SRC-3 was significantly extended in BR myeloma cells; this finding was similar to what was observed in their parental cells with ectopic overexpression of NSD2, and this protection occurred in a dose-dependent manner." (PMID 33589584, 2021). "Especially, NSD2 stimulates myeloma cell growth though inducing proto oncogene, c-Myc expression." (PMID 32826945, 2020). "Additionally, in multiple myeloma, NSD2 has been shown to be a regulator of DNA damage response that impacts resistance to chemotherapy." (PMID 30518758, 2018). "In addition, NSD2-induced stabilization of steroid receptor coactivator 3 (SRC3) is involved in resistance to bortezomib, a proteasomal inhibitor used in multiple myeloma therapy, while disrupting the interaction between NSD2 and SRC3 recovers the sensitivity to bortezomib." (PMID 41301842, 2025). "Notably, NSD2 has been shown to increase global levels of H3K36me2 while reducing H3K27me3, leading to large-scale reprogramming of chromatin architecture and transcriptional output, particularly in malignancies such as multiple myeloma." (PMID 41301842, 2025). "Overexpression and mutations of the three NSD family members (NSD1, NSD2, and NSD3) have been linked to several types of cancers, including lung cancer, breast cancer, prostate cancer, acute myeloid leukaemia, acute lymphoblastic leukaemia, and multiple myeloma." (PMID 37667522, 2023). "However, over the past decade, most functions of NSD2 have been identified in carcinogeneses, such as renal cell carcinoma, colorectal cancer, osteosarcoma, and multiple myeloma." (PMID 33718354, 2021). "Thus regulation of MMSET/NSD2 stability BRCA1-mediated ubiquitination could be explored for potential therapeutic interventions in multiple myeloma." (PMID 32826945, 2020). "Physical and functional interactions between NSD2 and other chromatin regulators, such as EZH2 and SMARCA2, further reprogram the chromatin landscape, promoting myeloma growth, altering enhancer activity, and sustaining drug resistance." (PMID 40563566, 2025). "Nuclear receptor-binding SET domain protein 2 (NSD2), also termed multiple myeloma SET domain or Wolf-Hirschhorn syndrome candidate 1, is a member of the SET histone methyltransferase family along with NSD1 and NSD3." (PMID 35354439, 2022). "Here, we identified the SET-domain containing histone methyltransferase (HMT) MMSET (multiple myeloma SET domain, a.k.a NSD2 or WHSC1), as a factor contributing to telomere-induced genomic instability." (PMID 32472076, 2020). "NSD2 (also known as WHSC1 and MMSET) was initially found to be deleted in Wolf-Hirschhorn syndrome (WHS) and rearranged with the immunoglobulin locus in 15%~20% multiple myeloma (MM) cases 4-5." (PMID 31692936, 2019). "This PROTAC inhibited proliferation of KMS11 and H929 multiple myeloma cells much more effectively than UNC6934, indicating that pharmacological degradation of NSD2 and IKZF1/3 is a superior therapeutic strategy to pharmacological antagonism of the NSD2-PWWP1 and chromatin PPIs." (PMID 37667522, 2023). "Furthermore, the RNA splicing processes supported by these isoform partners shed light on the diverse roles NSD2 plays in WHS and myeloma development." (PMID 33718354, 2021).
multiple myeloma (continued). "Nuclear receptor SET domain protein (NSD2) plays a fundamental role in the pathogenesis of Wolf–Hirschhorn Syndrome (WHS) and is overexpressed in multiple human myelomas, but its protein–protein interaction (PPI) patterns, particularly at the isoform/exon levels, are poorly understood." (PMID 33718354, 2021). "NSD2 (nuclear receptor-binding SET domain-containing 2), also known as MMSET (multiple myeloma SET domain) or WHSC1 (Wolf-Hirschhorn syndrome candidate 1) is a histone methyltransferase that belongs to the NSD family of SET domain-containing methyltransferases which also includes NSD1 and NSD3." (PMID 27604143, 2016). "The data also rules out abnormalities involving MAF, MAFB, MYC or NSD2/FGFR3, which are chromosomal translocations clinically relevant for multiple myeloma diagnosis." (PMID 40027317, 2024). "Therefore, targeting NSD2 with specific inhibitors could become part of a potential anti multiple myeloma therapy, which by impairing its interaction with SRC-3 (steroid receptor coactivator-3) facilitates overcoming the resistance of multiple myeloma to bortezomid, a proteasome inhibitor." (PMID 36011043, 2022).